SMN1 (survival of motor neuron 1, telomeric)
Description:
The SMN complex catalyzes the assembly of small nuclear ribonucleoproteins (snRNPs), the building blocks of the spliceosome, and thereby plays an important role in the splicing of cellular pre-mRNAs. Most spliceosomal snRNPs contain a common set of Sm proteins SNRPB, SNRPD1, SNRPD2, SNRPD3, SNRPE, SNRPF and SNRPG that assemble in a heptameric protein ring on the Sm site of the small nuclear RNA to form the core snRNP (Sm core). In the cytosol, the Sm proteins SNRPD1, SNRPD2, SNRPE, SNRPF and SNRPG are trapped in an inactive 6S pICln-Sm complex by the chaperone CLNS1A that controls the assembly of the core snRNP. To assemble core snRNPs, the SMN complex accepts the trapped 5Sm proteins from CLNS1A forming an intermediate. Within the SMN complex, SMN1 acts as a structural backbone and together with GEMIN2 it gathers the Sm complex subunits. Binding of snRNA inside 5Sm ultimately triggers eviction of the SMN complex, thereby allowing binding of SNRPD3 and SNRPB to complete assembly of the core snRNP. Ensures the correct splicing of U12 intron-containing genes that may be important for normal motor and proprioceptive neurons development. Also required for resolving RNA-DNA hybrids created by RNA polymerase II, that form R-loop in transcription terminal regions, an important step in proper transcription termination. May also play a role in the metabolism of small nucleolar ribonucleoprotein (snoRNPs).
Synonyms: SMN; SMNT; BCD541; SMA1; SMA2; SMA3; GEMIN1; TDRD16A; SMA; SMA4; SMA@; T-BCD541
Tractability: Small molecule: a structure with a bound ligand is known; a high-quality ligand is known; it belongs to a druggable protein family. PROTAC: UniProt records ubiquitination sites on it; ubiquitination databases record sites on it; a small molecule that binds it is known. Other modalities: an approved drug acts on it.
Target class: Methyl-lysine/arginine binding protein; Reader; Epigenetic regulator; Tudor domain
Chemical probes: ML104, ML200, ML372
Gene: Protein-coding gene on chromosome 5 (70,925,030 to 70,953,942, forward strand). Ensembl gene ENSG00000172062.
Subcellular location: Nucleus, gem; Nucleus, Cajal body; Cytoplasm; Cytoplasmic granule; Perikaryon; Cell projection, neuron projection; Cell projection, axon; Cytoplasm, myofibril, sarcomere, Z line
Subcellular location (Human Protein Atlas): Cytosol; Nuclear bodies
Pathways (Reactome):
Disease: SARS-CoV-2 modulates host translation machinery
Metabolism of RNA: snRNP Assembly
Gene Ontology:
Molecular function: identical protein binding; protein binding; RNA binding
Biological process: DNA-templated transcription termination; spliceosomal complex assembly; spliceosomal snRNP assembly; axonogenesis; mRNA processing; RNA splicing, via transesterification reactions
Cellular component: Cajal body; cytoplasm; cytoplasmic ribonucleoprotein granule; cytosol; Gemini of Cajal bodies; neuron projection; nuclear body; nucleoplasm; nucleus; perikaryon; SMN complex; SMN-Sm protein complex; axon; Z disc
Genetic constraint (gnomAD): Loss-of-function variants: 0 observed, 2.58 expected, observed/expected ratio (o/e) 0, 90% interval 0 to 1.12. That is too few expected variants to judge how well the gene tolerates losing a copy. Missense variants: 15 observed, 16.39 expected, observed/expected ratio (o/e) 0.92, 90% interval 0.61 to 1.41. Synonymous variants: 3 observed, 4.07 expected, observed/expected ratio (o/e) 0.74, 90% interval 0.33 to 1.7.
Homologues: Orthologues: chimpanzee SMN2 (100% identical), macaque SMN1 (93% identical), dog SMN (85% identical), mouse Smn1 (82% identical), rat Smn1 (75% identical), tropical clawed frog smn1 (54% identical), zebrafish smn1 (49% identical), Caenorhabditis elegans smn-1 (23% identical), Drosophila melanogaster Smn (20% identical). Paralogues in human: SMN2 (100% identical), SMNDC1 (19% identical).
Diseases named in the same sentence as SMN1 in open-access papers:
SMN1 is named in the same sentence as 163 diseases in open-access papers, as found by Europe PMC text mining. Sharing a sentence is not in itself a finding about the gene and the disease. The quoted sentences say what the papers report.
spinal muscular atrophy (571 papers, 2005 to 2026). A motor neuron disease that affect the muscles, and characterized by muscle weakness and atrophy resulting from progressive degeneration and irreversible loss of the anterior horn cells in the spinal cord (i.e., lower motor neurons) and the brain stem nuclei. "Spinal muscular atrophy (SMA) is an autosomal recessive neurodegenerative disorder caused by mutation of the survival motor neuron 1 (SMN1) gene." (PMID 41958916, 2026). "Spinal muscular atrophy (SMA) is a neurodegenerative disorder resulting from mutations in SMN1 that manifest as progressive muscle weakness and atrophy." (PMID 41817636, 2026). "Spinal muscular atrophy (SMA) is a devastating neuromuscular disorder caused by mutations in the survival motor neuron 1 (SMN1) gene leading to decreased SMN protein levels and motor neuron dysfunction." (PMID 41885937, 2026). "Spinal muscular atrophy (SMA) is a severe genetic neuromuscular disorder caused by bi-allelic deletions or pathogenic SMN1 variants." (PMID 41718420, 2026). "Spinal muscular atrophy (SMA) is an autosomal recessive neuromuscular disorder caused by SMN1 gene variants, leading to the degeneration of anterior horn cells in the spinal cord." (PMID 41825231, 2026). "Spinal muscular atrophy (SMA) results from SMN1 gene loss-of-function (LOF), with disease severity directly linked to the level of remaining SMN protein." (PMID 41398093, 2026). "Spinal muscular atrophy (SMA) is a rare genetic neuromuscular disease caused by deletions or mutations of the survival motor neuron 1 (SMN1) gene." (PMID 40956616, 2025). "Spinal muscular atrophy (SMA) is an autosomal recessive disease most commonly caused by homozygous deletion of the SMN1 gene." (PMID 40094379, 2025). "Spinal muscular atrophy (SMA) is a rare autosomal recessive neuromuscular disease caused by biallelic mutations in the survival motor neuron (SMN1) gene." (PMID 39904776, 2025). "PLP variants in SMN1 gene are associated with spinal muscular atrophy (SMA), recognized as the leading genetic cause of infant mortality." (PMID 41303398, 2025). "Spinal muscular atrophy (SMA) is a severe neurodegenerative disease caused by defects in the survival motor neuron 1 (SMN1) gene." (PMID 40384931, 2025). "5q-associated Spinal Muscular Atrophy (SMA) is a hereditary neuromuscular disorder caused by mutations in the survival of motor neuron 1 (SMN1) gene, leading to progressive muscle weakness, and atrophy." (PMID 41369341, 2025). "Spinal muscular atrophy (SMA) is an autosomal recessive neuromuscular disorder caused by biallelic SMN1 gene loss, leading to motor neuron degeneration and progressive muscle weakness." (PMID 41303705, 2025). "Onasemnogene abeparvovec (OA) is an adeno-associated virus vector-based gene therapy indicated for the treatment of paediatric patients with spinal muscular atrophy(SMA) with biallelic mutations in the survival motor neuron 1 (SMN1) gene." (PMID 40329332, 2025). "Spinal muscular atrophy (SMA) is a neuromuscular disorder caused by the loss of the SMN1 gene, with an estimated birth prevalence of about 1 in 10,000." (PMID 40804727, 2025). "Spinal muscular atrophy (SMA) is a severe autosomal recessive neuromuscular disorder resulting from the loss of the survival motor neuron 1 (SMN1) gene." (PMID 40804727, 2025). "Spinal muscular atrophy (SMA) is a rare autosomal recessive neuromuscular disorder caused by homozygous deletions or mutations in the survival motor neuron 1 (SMN1) gene, leading to deficient levels of the SMN protein." (PMID 40364205, 2025). "Spinal muscular atrophy (SMA) is a neuromuscular disease caused by deletions or mutations in the survival motor neuron 1 (SMN1) gene." (PMID 41249338, 2025). "Spinal Muscular Atrophy (SMA) is a neuromuscular disorder precipitated by mutations or deletions in the Survival Motor Neuron 1 (SMN1) gene." (PMID 40640928, 2025).
spinal muscular atrophy (continued). "Spinal Muscular Atrophy is an autosomal dominant disease caused by mutations and deletions within the SMN1 gene, with predominantly childhood onset." (PMID 39810393, 2025). "Branaplam was originally developed as a splice enhancer of exon 7 in the SMN2 gene, which increases full-length SMN2 protein and compensates for loss of SMN1 function in spinal muscular atrophy." (PMID 41311869, 2025). "This issue concerns regions related to numerous disease-associated genes, such as SMN1 (spinal muscular atrophy) and CFC1 (congenital heart defects)." (PMID 40244459, 2025). "Spinal muscular atrophy (SMA) is primarily caused by deletions or homozygous mutations in the survival motor neuron 1 (SMN1) gene." (PMID 40406043, 2025). "Spinal muscular atrophy (SMA) is a neuromuscular disorder caused by homozygous deletions or mutations in the SMN1 gene, leading to progressive motor neuron degeneration." (PMID 40137462, 2025). "Spinal muscular atrophy (SMA) is a rare neurodegenerative disease due to a homozygous deletion or mutation of the survival motor neuron (SMN1) gene, resulting in decreased SMN protein production." (PMID 39815373, 2025). "SMN1, a gene that is autosomal recessively linked to spinal muscular atrophy, constitutes another example of a clinically relevant but difficult-to-resolve genomic locus since short reads cannot completely discriminate it from SMN2." (PMID 40244459, 2025). "SMN1 gene, associated with spinal muscular atrophy was identified with a carrier frequency of approximately 1:30, higher than in the Caucasian populations." (PMID 41303398, 2025). "Spinal muscular atrophy (SMA) is a rare neuromuscular disease caused by biallelic mutations in the SMN1 gene, leading to progressive muscle weakness due to degeneration of the anterior horn cells." (PMID 39904776, 2025). "Spinal muscular atrophy (SMA) is a severe genetic neuromuscular disorder resulting from homozygous mutations in the SMN1 gene." (PMID 40724593, 2025). "Spinal muscular atrophy (SMA) is a neurodegenerative disorder resulting from mutations in the SMN1 gene." (PMID 40465163, 2025). "Spinal muscular atrophy (SMA) is a genetic neuromuscular disorder caused by mutations in the SMN1 gene." (PMID 41028013, 2025). "Spinal muscular atrophy (SMA) is an autosomal recessive neuromuscular disease characterized by survival motor neuron 1 (SMN1) gene mutation and degeneration of spinal motor neurons, resulting in generalized muscle hypotonia, weakness, and atrophy." (PMID 40275389, 2025). "Spinal muscular atrophy (SMA) is an inherited lower motor neuron disease caused by abnormalities in SMN1, with progressive muscle atrophy as its main clinical feature." (PMID 40150095, 2025). "Only in very few cases, where ASOs can introduce or improve a compensatory mechanism, recessive conditions are suitable such as in SMN1-related spinal muscular atrophy where ASOs target indirectly the disease associated gene." (PMID 40687881, 2025). "Spinal muscular atrophy (SMA) is a degenerative motor neuron disease caused by a deficiency of Survival of Motor Neuron (SMN) protein resulting from mutations in the SMN1 gene." (PMID 41278815, 2025). "The application of the first gene therapy approach for spinal muscular atrophy (SMA) linked with variants in survival motor neuron 1 (SMN1) provides potential strategies for intervention for SMARD1." (PMID 40686563, 2025). "Spinal muscular atrophy (SMA) is caused by a defect in the SMN1 gene, leading to muscle weakness and motor neuron loss." (PMID 39048567, 2024). "ASO therapy has also been investigated in the clinic for spinal muscular atrophy, caused by changes in the SMN1 gene that decrease the SMN protein and disrupt the functioning of motor neurons, affecting muscle control." (PMID 39272802, 2024). "Spinal muscular atrophy (SMA) is a rare degenerative disorder with loss of motor neurons caused by mutations in the SMN1 gene." (PMID 39325116, 2024).
spinal muscular atrophy (continued). "Spinal muscular atrophy (SMA) is a genetic disorder primarily caused by mutations in the SMN1 gene, leading to motor neuron degeneration and muscle atrophy, affecting multiple organ systems." (PMID 39200246, 2024). "Spinal muscular atrophy (SMA) is caused by homozygous loss of the SMN1 gene with SMN2 gene copy number correlating with disease severity." (PMID 39139818, 2024). "5q-associated spinal muscular atrophy (SMA) is a motoneuron disease caused by mutations in the survival motor neuron 1 (SMN1) gene." (PMID 38750052, 2024). "Deletion or disruption of SMN1 is associated with spinal muscular atrophy (SMA) and its paralogue, SMN2, is the target of one of the most successful ASO-mediated gene therapies." (PMID 39372794, 2024). "SMN protein forms the oligomeric core of this complex, and missense mutations in the human SMN1 gene are known to cause Spinal Muscular Atrophy (SMA)." (PMID 39492846, 2024). "Spinal muscular atrophy (SMA) is a progressive neuromuscular disorder caused by mutations in SMN1, with disease severity influenced by the number of SMN2 copies." (PMID 39720178, 2024). "Spinal muscular atrophy (SMA) is a rare autosomal recessive neurodegenerative disorder stemming from a deletion or mutation in the Survival Motor Neuron 1 SMN1 gene." (PMID 39200246, 2024). "The 5q Spinal Muscular Atrophy (SMA) is a hereditary autosomal recessive disease caused by defects in the survival motor neuron (SMN1) gene encoding survival motor neuron (SMN) protein." (PMID 39456991, 2024). "Spinal muscular atrophy, a common muscular disorder, most commonly caused by a copy number change in the SMN1 gene and modified by the copy numbers of SMN2, is also missed by WES." (PMID 38167091, 2024). "5q-Spinal muscular atrophy (5q-SMA) is one of the most common neuromuscular diseases due to homozygous mutations in the SMN1 gene." (PMID 39000416, 2024). "Spinal muscular atrophy (SMA) is a recessive developmental disorder caused by the genetic loss or mutation of the gene SMN1 (survival of motor neuron 1)." (PMID 39264856, 2024). "Spinal muscular atrophy (SMA) is an autosomal recessive neuromuscular disorder that is caused by mutations in the SMN1 gene." (PMID 39596864, 2024). "Spinal muscular atrophy (SMA) is a severe neuromuscular disorder that is caused by mutations in the survival motor neuron 1 (SMN1) gene, hindering the production of functional survival motor neuron (SMN) proteins." (PMID 38893532, 2024). "Spinal muscular atrophy (SMA) stands as a severe inherited neuromuscular disorder resulting from the deletion or mutation of survival motor neuron gene 1 (SMN1)." (PMID 39048567, 2024). "Spinal muscular atrophy (SMA) is a neuromuscular disorder caused by recessive pathogenic variants affecting the survival of motor neuron (SMN1) gene (localized on 5q)." (PMID 38470509, 2024). "Spinal muscular atrophy (SMA) is an autosomal recessive neurodegenerative disease caused by a biallelic mutation of the neuronal survival gene SMN1 on chromosome 5q." (PMID 39684197, 2024). "The importance of SMN in humans was first recognized when deletions or mutations in the SMN1 gene caused Spinal Muscular Atrophy (SMA), a leading genetic disease." (PMID 39598305, 2024). "Spinal muscular atrophy (SMA) is an autosomal recessive disease caused by the deletion or mutation of the survival motor neuron 1(SMN1) gene and the resulting insufficient expression of the SMN protein." (PMID 38887183, 2024). "Spinal muscular atrophy (SMA) is a neuromuscular disorder caused by mutations or deletions in the survival motoneuron 1 (SMN1) gene, resulting in deficiency of the SMN protein that is essential for motoneuron function." (PMID 39246602, 2024). "Spinal muscular atrophy (SMA) is a rare autosomal recessive hereditary neuromuscular disease caused by survival motor neuron 1 (SMN1) gene deletion or mutation." (PMID 38468256, 2024).
spinal muscular atrophy (continued). "Defect in the SMN1 gene causes spinal muscular atrophy (SMA), which shows loss of motor neurons, muscle weakness and atrophy." (PMID 39048567, 2024). "Spinal muscular atrophy (SMA) is an autosomal recessive neuromuscular disorder primarily caused by homozygous deletions in exon 7 of the survival motor neuron 1 (SMN1) gene, leading to lower motor neuron degeneration." (PMID 39088538, 2024). "Spinal muscular atrophy (SMA) is an autosomal recessive disease caused by mutations in the survival motor neuron 1 (SMN1) gene on chromosome 5, leading to the degeneration of lower motor neurons." (PMID 39398417, 2024). "Quite recently, single-dose delivery of the SMN gene (SMN1 AC005031) to infants with spinal muscular atrophy (SMA) type 1 using Zolgensma (adeno-associated virus serotype 9) has been shown to be crucial for patients survival." (PMID 39595938, 2024). "These introduced genes have the potential to rectify the loss of gene function caused by pathological mutations, such as the instance of the SMN1 gene in spinal muscular atrophy." (PMID 38396996, 2024). "Spinal muscular atrophy (SMA) is an autosomal recessive neuromuscular disorder due to deletion or mutation of survival motor neuron 1 (SMN1) gene." (PMID 38894621, 2024). "Spinal muscular atrophy (SMA) is an intractable neuromuscular disorder primarily caused by homozygous deletions in exon 7 of the SMN1 gene." (PMID 39088538, 2024). "Low levels of SMN protein due to deletions or mutations of SMN1 lead to spinal muscular atrophy (SMA), a major genetic disease linked to infant mortality." (PMID 38214229, 2024). "Spinal muscular atrophy (SMA) is a neurodegenerative disease caused by mutations in the SMN1 gene, leading to motor neuron degeneration and muscle weakness." (PMID 39707395, 2024). "Spinal muscular atrophy (SMA) is an autosomal recessive neuromuscular condition caused by pathogenic variants in the SMN1 gene which leads to the degeneration and loss of alpha motor neurons in the anterior horn of the spinal cord." (PMID 39051410, 2024). "Spinal muscular atrophy (SMA) is a neuromuscular disease caused by a homozygous deletion or mutation in the survival of motoneuron- (SMN1) gene, leading to degeneration of alpha-motoneurons and thus to progressive muscular weakness." (PMID 38633535, 2024). "AAV gene therapy of the spinal cord is now FDA-approved for the treatment of infantile Spinal Muscular Atrophy (SMA) with a single IV dose of 2 × 1014 vector genome per kg (vg/kg) of the scAAV9 encoding the Survival Motor Neuron 1 (SMN1) gene." (PMID 38543056, 2024). "Spinal muscular atrophy (SMA) is a hereditary neuromuscular disease resulting from a recessively inherited mutation in the SMN1 gene on chromosome 5q." (PMID 39189230, 2024). "Inherited motor neuron disease in childhood is most frequently linked to mutations in the SMN1 gene located on chromosome 5q13, resulting in spinal muscular atrophy (SMA)." (PMID 39457470, 2024). "Spinal muscular atrophy (SMA) is an autosomal neuromuscular disease primarily caused by a mutation in the survival motor neuron-1 (SMN1) gene, which is located on chromosome 5q13 and responsible for the proper survival of motor neurons." (PMID 38920997, 2024). "Spinal muscular atrophy (SMA) is a relatively prevalent genetic disorder caused by biallelic mutations in SMN1 gene and characterised by progressive degeneration of lower motor neurons." (PMID 38600653, 2024). "These include spinal muscular atrophy (SMA) caused by mutations in the survival motor neuron 1 (SMN1) gene and amyotrophic lateral sclerosis 10 (ALS10) caused by mutations in the TAR DNA binding protein or TDP-43 gene." (PMID 39070547, 2024).